AIM2 (absent in melanoma 2)
Diseases named in the same sentence as AIM2 in open-access papers (continued):
Sharing a sentence is not in itself a finding about the gene and the disease.
leukemia (6 papers, 2022 to 2024). A malignant (clonal) hematologic disorder, involving hematopoietic stem cells and characterized by the presence of primitive or atypical myeloid or lymphoid cells in the bone marrow and the blood. "Together, the results demonstrated that ATRA+MRT treatment can activate the AIM2 inflammasome-caspase-1 pathway to inhibit p21 proteasomal degradation, promoting myeloid differentiation and cell growth arrest in leukemia cells." (PMID 38466568, 2024). "We focused on NLRP3 and/or the AIM2 inflammasome because the cluster 9 cells from our scRNA-seq analysis of Usp18+/Δ primary murine leukemia cells predicted inflammasome activation." (PMID 36646704, 2023). "In summary, here we have discovered that curcumin can induce leukemia cell death by increasing apoptosis and pyroptosis and that activated AIM2, IFI16, and NLRC4 inflammasomes play a key role in this process." (PMID 35435150, 2022). "Thus, we propose that AIM2 inflammasome-mediated accumulation of p21 can turn differentiation therapy into an irreversible process in leukemia cells." (PMID 38466568, 2024). "Mechanistically, blocking autophagic clearance resulted in the accumulation of cytosolic dsDNA fragments, activating the AIM2 inflammasome-caspase-1 pathway and consequently inhibiting p21 proteasomal degradation, which promoted myeloid differentiation and cell growth arrest in leukemia cells." (PMID 38466568, 2024). "In this study, we found that curcumin induced the expression of NLRC4, AIM2, and IFI16 inflammasomes by upregulated ISG3 transcription factor complex in leukemia cell U937, which activates caspase 1 and promotes cleavage of GSDMD." (PMID 35435150, 2022). "Likewise, AIM2 shRNA treatment reduced the ATRA+MRT-mediated upregulation of CD11b and p21 protein expression in THP-1 cells, another human leukemia cell line." (PMID 38466568, 2024). "Thus, the autophagosome formation inhibition-mediated activation of AIM2 inflammasome can also synergize with a molecular-targeted drug, FLT3 inhibitor, to induce irreversible differentiation in leukemia cells with FLT3-ITD even in the presence of FGF2." (PMID 38466568, 2024). "In this study, we demonstrated that curcumin induced the expression of AIM2, IFI16, and NLRC4 inflammasomes in leukemia cells U937 by increasing the expression levels of ISG3 transcription factor complex, which activated caspase 1, promoted cleavage of GSDMD, and induced pyroptosis." (PMID 35435150, 2022).
liver cancer (6 papers, 2016 to 2025). An epithelial or non-epithelial malignant neoplasm that arises from the liver. "Here we showed that AIM2 expression was significantly decreased in liver cancer tissues, and loss of its expression was significantly correlated with more advanced tumor progression." (PMID 27167192, 2016). "In an intriguing analysis of the molecular landscape of liver cancer, the expression profile of AIM2 has emerged as a pivotal determinant of tumor progression." (PMID 40386782, 2025). "In this study, we found that the upregulation of AIM2 effectively inhibits the malignancy of liver cancer cells, whereas its downregulation amplifies malignant characteristics of liver cancer cells." (PMID 39222064, 2024). "AIM2 has demonstrated downregulated in liver cancer tissues, but enhancing AIM2 expression can inhibit the malignancy of liver cancer cells." (PMID 39222064, 2024). "In this study, we found that overexpression of AIM2 in liver cancer cells exerts an inhibitory effect on M2 phenotype macrophage polarization." (PMID 39222064, 2024). "This study inaugurally demonstrated that AIM2 activates autophagy and influences macrophage polarization, playing a role in liver cancer progression." (PMID 39222064, 2024). "In conclusion, this study was designed to explore the regulatory role of AIM2 expression in liver cancer cells." (PMID 39222064, 2024). "In liver cancer cells, activation of the AIM2 inflammasome promotes autophagy and inhibits M2‐type polarization of macrophages." (PMID 39222064, 2024). "Research indicates that the AIM2‐involved inflammasome plays a key regulatory role in the development and progression of liver cancer." (PMID 39222064, 2024). "Further in vitro experiments showed that an overexpression of AIM2 in liver cancer cells favors the inhibition of M2 macrophage polarization." (PMID 39222064, 2024). "The impact of AIM2 on the malignant biological behaviors of liver cancer cells in vitro, and studied the effect of liver cancer cells on the M2 polarization of macrophages were investigated." (PMID 39222064, 2024). "Through these efforts, we have initially elucidated the mechanisms connecting AIM2 to the onset and progression of liver cancer, thereby offering valuable insights and a groundwork for future clinical treatments." (PMID 39222064, 2024). "In liver cancer, the expression level of AIM2 is often decreased, and exogenous overexpression of AIM2 can suppress cancer cells progression and development by inducing pyroptosis and inhibiting the mTOR-S6K1 pathway." (PMID 37705746, 2023). "Similar to the NLRP3 inflammasome in liver cancer, the AIM2 inflammasome also possesses similar anti-tumor effects." (PMID 37705746, 2023). "Previous studies have shown that AIM2 inflammasomes inhibit the occurrence and development of liver cancer, while promotes the occurrence and development of skin SCC." (PMID 36248785, 2022). "In order to define the expression status of AIM2 in liver cancer tissues, 113 clinical HCC patients were recruited for the investigation." (PMID 27167192, 2016). "Expression of AIM2 in the liver cancer cells were significantly decreased compared with corresponding distal non-cancerous liver tissues." (PMID 27167192, 2016). "Further in vivo and in vitro studies demonstrated that exogenous overexpression of AIM2 inhibited malignancies of HCC cells through suppressing mTOR-S6K1 pathway, which suggested a protective role of AIM2 against liver cancers." (PMID 27167192, 2016). "In this study, we detected the expression of AIM2 in clinical liver cancer specimen, analyzed the correlation between its expression and disease progression, and further investigated its role in malignant behaviors of HCC cells in cellular and animal models." (PMID 27167192, 2016). "Additionally, we established a subcutaneous tumor model in nude mice following the knockdown of AIM2 in LV-D and LV-veh mouse liver cancer cells." (PMID 39479454, 2024).
liver cancer (continued). "Additionally, it is important to investigate how AIM2 triggers the modulation of macrophage polarization induced by liver cancer cells." (PMID 39222064, 2024). "Therefore, it indicated that therapeutic strategy by upregulating AIM2 may pave a new avenue for manipulating liver cancer, and pharmacological targeting of mTOR-S6K1 pathway may be beneficial in AIM2-deficient tumors." (PMID 27167192, 2016). "Research indicates that activation of the AIM2/caspase‐1 inflammasome can promote autophagy and apoptosis in HCC cells, potentially exerting an inhibitory effect on liver cancer progression." (PMID 39222064, 2024). "However, when AIM2 is inhibited, the activity of the mTOR/S6K1 pathway is enhanced, promoting the development of liver cancer." (PMID 39222064, 2024). "Firstly, expression and location of AIM2 was detected by IHC in the liver cancer tissues and corresponding non-cancerous liver tissues from 49 HCC patients." (PMID 27167192, 2016).
liver diseases (6 papers, 2015 to 2025). "AIM2 plays a complex role in liver diseases, contributing to the progression of NAFLD and NASH through its inflammasome activity and cooperation with TLR9 signaling." (PMID 39158380, 2025). "This study provides a detailed description of the P2X7R-NLRP3 and AIM2 inflammasomes in the liver of patients carrying different hepatic diseases (viral or metabolic damage)." (PMID 35806450, 2022). "In this review, we discuss the importance of AIM2 in the pathogenesis of liver diseases, including NAFLD, HBV infection, fibrosis, cirrhosis, and HCC." (PMID 32906750, 2020). "The study of AIM2 in different liver diseases is supported by the fact that inflammation, either sterile (e.g., NAFLD and NASH) or induced by pathogens (e.g., viral hepatitis), is the origin of most of these diseases." (PMID 32906750, 2020). "Our data corroborate the relevant role played by AIM2 in virus-related liver diseases." (PMID 35806450, 2022). "Lastly, the contribution of AIM2 regulators such as p202, POP3, or TRIM11 to liver diseases is unknown and awaits specific studies." (PMID 32906750, 2020). "The effect of liver disease on gene expression was confirmed in multivariable models after adjustment for potential confounders (age, sex, BMI): all the inflammasome components (P2X7R, P2X4R, NLRP3, CASP1, AIM2, IL-2) were significantly related to the liver disease (0.0007 < p <0.037)." (PMID 35806450, 2022). "It is also conceivable that AIM2 could have positive or negative effects in a particular liver disease, depending on the cell type in which it is activated (immune vs. non-immune cell) or the stage of the disease." (PMID 32906750, 2020). "Expression analysis for various inflammasomes in animal model suggested that NLRP1, NLRP3, and AIM2 were highly expressed in Kupffer cells and liver sinusoidal endothelial cells, while virtually absent in primary cultured hepatocytes in inflammatory and hepatic disease conditions." (PMID 31551961, 2019).
polyarthritis (6 papers, 2015 to 2024). "Altogether, these results indicated that AIM2 is required for the development of polyarthritis in the context of DNase2-deficiency." (PMID 26114879, 2015). "Therefore, to elucidate the mechanism of Aim2-deficiency ameliorating DNase2-/--associated polyarthritis, we next assessed systemic signs of inflammation in these mice." (PMID 26114879, 2015). "The role of AIM2 and self-DNA in driving polyarthritis has been proposed, with CHIKV infection-mediated cytopathic effects conceivably providing the DNA to stimulate this pathway." (PMID 31211814, 2019). "Note added in proof: While this manuscript was under review, Ellen Gravallese and colleagues have published a likewise approach of studying the role of AIM2 in the context of Dnase2-/- x Ifnar1-/- induced polyarthritis." (PMID 26114879, 2015). "Furthermore, Aim2 deletion added to Dnase2a-Ifnar1 double-deficiency ameliorated the polyarthritis phenotype in these mice, indicating AIM2 inflammasome activation in the absence of DNASE2A contributes as well to this disease." (PMID 33717156, 2021). "However, given the fact that IL-18 deficiency does not protect Dnase2-deficient animals from polyarthritis or pro-inflammatory gene expression, Aim2-dependent IL-18 production or maturation appears to be an epiphenomenon rather than a cause in this disease model." (PMID 26114879, 2015).
subarachnoid hemorrhage (6 papers, 2020 to 2024). A serious neurological disorder characterized by intracranial hemorrhage into the subarachnoid space. "AIM2 also has a role in early brain injury, following subarachnoid haemorrhage, as patients had significantly increased cerebral spinal fluid (CSF) levels of AIM2, and neuronal damage was reversed in AIM2 and caspase‐1 KO models." (PMID 35832835, 2022). "Inhibition of the AIM2 inflammasome following subarachnoid hemorrhage (SAH) decreased GMDSD-induced pyroptosis, a form of programmed cell death." (PMID 33206327, 2021). "Current studies have shown that a variety of inflammasomes are involved in the process of neuronal cell pyroptosis, such as AIM2, NLRP1, and NLRP3, after subarachnoid hemorrhage, among which NLRP3 is the best studied." (PMID 38044382, 2023).
Alzheimer disease (5 papers, 2019 to 2025). A progressive, neurodegenerative disease characterized by loss of function and death of nerve cells in several areas of the brain leading to loss of cognitive function such as memory and language. "For instance, the AIM2-PANoptosome is involved in Alzheimer’s disease (AD), as AIM2 knockout suppresses key AD-related events like Aβ-deposition and microglial activation." (PMID 40568592, 2025). "Of interest, studies have indicated a role for the Aim2/AIM2 proteins in neuroinflammation and neurodegenerative diseases, including Alzheimer’s disease (AD)." (PMID 31771614, 2019). "Furthermore, we present a comprehensive review of the roles of AIM2 in neurodegenerative diseases, including Alzheimer’s disease (AD) and Parkinson’s disease (PD)." (PMID 39076969, 2024).
bladder cancer (5 papers, 2022). "In this study, high levels of AIM2 were found to be a protective factor for bladder cancer, though its level of expression and prognostic value were shown to be contradictory across different tumors." (PMID 35846123, 2022). "The Univariate Cox regression analysis revealed that eight PRGs (PRKACA, GSDMB, CASP9, GSDMD, CASP6, CASP8, AIM2, and CASP1) were significantly correlated with the prognosis in bladder cancer." (PMID 36120583, 2022).
colorectal tumors (5 papers, 2020 to 2023). "Even though AIM2-deficient mice produce similar levels of IL-1 and IL-18, more colorectal tumors are found in AIM2-deficient mice than in the wild-type mice." (PMID 35734577, 2022). "Results showed that tumor weights and sizes derived from AIM2-overexpressed HCT116 cells were notably reduced compared to their negative controls, suggesting the inhibitory effect of AIM2 on colorectal tumor growth." (PMID 33291082, 2020).
Coronary Artery Disease (5 papers, 2022 to 2025). "This is consistent with reports linking AIM2 to endothelial dysfunction in coronary artery disease and inflammation-mediated bone loss following chemotherapy." (PMID 40940808, 2025).
lymph node metastasis (5 papers, 2020 to 2025). "Reduced AIM2 expression was strongly linked to lymph node metastasis, intravascular tumor thrombosis, diminished survival rates, and unfavorable prognosis." (PMID 39744568, 2025). "Furthermore, loss of AIM2 was significantly associated with tumor size, lymph node metastasis (LNM) and tumor, node, metastases (TNM) staging, as well as poor prognosis in GC patients." (PMID 33859277, 2021). "In the present work, we provide evidence that AIM2 was commonly downregulated in human CRC and loss of AIM2 significantly correlated with tumor size, depth of invasion, lymph node metastasis (LNM) and TNM (Tumor, Node, Metastases) stage in patients suffering from CRC." (PMID 33291082, 2020). "Decreased AIM2 expression was found to be correlated with unfavorable prognostic outcomes, including lymph node metastasis and reduced 5-year overall and disease-specific survival rates in individuals diagnosed with RCC." (PMID 39744568, 2025). "Lower levels of AIM2 were correlated to both clinicopathological features, such as the depth of invasion, higher TNM clinical stage and lymph node metastasis, as well as to poor prognosis." (PMID 40002808, 2025). "Particularly, the authors found that although AIM2 expression was higher in adjacent normal hypopharyngeal tissues than HSCC tissues, lower expression was positively correlated with lymph node metastasis and intravascular tumor thrombus, implying the poor prognosis of patients with HSCC." (PMID 40002808, 2025). "Second, given that it is difficult to establish the presence of lymph node metastasis in many patients, the effect of the expression of AIM2, DFNB59, NLRP11 and PRTN3 on T staging was not fully investigated." (PMID 35281845, 2022). "Further analysis indicated that AIM2 levels were lower in tumor tissues with lymph node metastasis (LNM) than those without LNM (P < 0.001)." (PMID 33859277, 2021).
parasitemia (5 papers, 2018 to 2025). "Furthermore, the activation of the AIM2 inflammasome and caspase-1-dependent signaling negatively regulate host immune responses against lethal P. yoelii YM infection, and parasitemia is reduced in infected AIM2- and caspase-1-deficient mice compared with wild-type mice." (PMID 39548522, 2024). "We infected Aim2−/−, Nlrp3−/−, and Casp1−/− mice with YM-iRBCs, and found that parasitemias in Aim2−/−, Nlrp3−/−, and Casp1−/− mice were markedly lower than those in WT mice." (PMID 30470758, 2018). "Inflammasomes, which are multiprotein complexes, are activated during parasite infection, particularly NOD-, LRR- and pyrin domain-containing protein 3 (NLRP3) and absent in melanoma 2 (AIM2), which subsequently activate caspsase-1 and are responsible for IL-1β processing and secretion." (PMID 39614280, 2024).
acute hepatitis B (4 papers, 2013 to 2024). "AIM2 expression was first reported in peripheral blood mononuclear cells (PBMCs) of patients with acute hepatitis B (AHB) and chronic hepatitis B (CHB)." (PMID 32906750, 2020). "Interestingly, AIM2 levels were high in acute hepatitis B (AHB) compared to CHB and negatively correlated with serum HBV viral load and hepatitis B envelope antigen (HBeAg), uncovering that AIM2 is involved in HBV immune clearance." (PMID 37465759, 2023). "Besides NLRP3 inflammasome, IFI16 and AIM2 inflammasomes participate in the pathological process of hepatitis B, and NALP3 inflammasome may sense HCV infection in hepatocytes." (PMID 38817443, 2024). "Similar results were obtained in the recent Wu study focusing on the relationship between AIM2 expression and acute and chronic hepatitis B infection, suggesting that AIM2 plays an important role in both HBV-GN and hepatitis B infection." (PMID 24325587, 2013).
asthma (4 papers, 2020 to 2025). "Epidemiological studies consistently correlate high PM2.5 levels with increased asthma incidence and exacerbation rates, positioning the AIM2 inflammasome as a potential therapeutic target for pollutant-associated airway injury." (PMID 41394843, 2025). "AIM2-dependent IL-1β secretion from macrophages was shown during influenza A infection, and upregulation of the inflammasome-related AIM2 gene was shown during asthma exacerbation by rhinovirus-A16, though very little is known about the AIM2 function during rhinovirus infection." (PMID 37662905, 2023). "scRNA-seq has identified non-classical monocytes (CD14+CD16+) in severe asthma lungs that exhibit primed inflammasome states (high AIM2, CASP1)." (PMID 41394843, 2025). "Crucially, we contextualize pyroptosis within distinct asthma endotypes, proposing that allergen-driven, NLRP3-dominated pathways may underpin Th2-high/eosinophilic inflammation, while pollutant/viral-triggered, non-canonical/AIM2 pathways may favor Th2-low/neutrophilic phenotypes." (PMID 41394843, 2025).
dermatitis (4 papers, 2019 to 2023). An inflammatory process affecting the skin. "In order to gain further insight into how CO ameliorates IMQ-induced skin inflammation, we examined the impact of CO on the expression of AIM2 inflammasome components in skin lesions and of serum IL-17A in the mice treated with IMQ." (PMID 36982727, 2023). "Kopfnagel found that human keratinocytes express AIM2 and respond to dsDNA with IL-1β secretion, indicating that the AIM2 inflammasome is a trigger for skin inflammation." (PMID 32528469, 2020). "This study provides evidence for the inhibitory activity of CO, an ethanolic extract of Cornus officinalis seed, on AIM2-inflammasome activation and its potential therapeutic effect on psoriatic-like skin inflammation induced by IMQ, to which the AIM2 inflammasome is known to contribute." (PMID 36982727, 2023).
diabetic nephropathy (4 papers, 2024 to 2025). "Collectively, we found that AIM2 expression was elevated in proximal renal tubular in vivo and vitro model of diabetic nephropathy." (PMID 39659523, 2024). "Furthermore, increased STING, AIM2, IRF3, NLRP3, Caspase-1, and IL-1β levels in the serum of diabetic nephropathy (DN) patients and their whole-blood immune cells have shown overexpressed STING and AIM2 mRNAs." (PMID 38339107, 2024).